GSDMB (gasdermin B)
Diseases named in the same sentence as GSDMB in open-access papers (continued):
Sharing a sentence is not in itself a finding about the gene and the disease.
asthma (continued). "Rs7216389, a SNP in the GSDMB gene on chromosome 17q12-21, was first linked to childhood asthma in a genome-wide associations study in 2007." (PMID 33810791, 2021). "An interesting example of how sQTL mapping can help to gain insight into the mechanisms underlying GWAS associations is the case of asthma and the gene gasdermin b (GSDMB)." (PMID 33526779, 2021). "Genome‐wide sequencing and functional genes indicate that single nucleotide polymorphisms of GSDMB are related to the increased susceptibility of ulcerative colitis and Crohn's disease, as well as asthma exacerbations and antiviral pathways." (PMID 34459122, 2021). "The rs7216389 SNP in gasdermin B gene (GSDMB) increased the risk of childhood asthma with each C to T substitution in a dose-dependent pattern (additive model, aOR 1.32, 95% CI 1.11–1.57)." (PMID 33810791, 2021). "For this, we focused our attention on the asthma seed gene GSDMB, one of several genes on 17q21 that harbors the most replicated asthma-susceptibility locus identified by GWAS63." (PMID 32041952, 2020). "Associations have been shown between GSDMA gene and asthma and, between GSDMB gene and asthma or early childhood asthma with severe exacerbations." (PMID 33133517, 2020). "A large GWAS of European 180,129 adults/children with asthma and/or AR and/or eczema and 180,709 healthy controls showed that GSDMB gene (rs921650 A) is a stronger risk factor for asthma or hay fever than for eczema." (PMID 33133517, 2020). "The gene targets of both miR-155 and miR-15a include genes that have been previously associated with asthma susceptibility in published asthma GWAS including GSDMB and TSLP." (PMID 33291534, 2020). "MiR-15a was also associated with the in utero expression of GSDMB (adjusted p = 0.0002), a known childhood asthma gene and with asthma exacerbations (p = 0.0009) in Asthma BRIDGE." (PMID 33291534, 2020). "ORMDL3 and GSDMB are promising candidates in this regard because expression levels of these genes are highly correlated with asthma risk genotypes at 17q in blood cells and are also induced by HRV infection." (PMID 32887352, 2020). "A meta‐analysis of GWAS of 2144 asthmatic Puerto Ricans and 2893 healthy controls (adults & children) found GSDMB gene (rs2305480, G—> A and rs11078927, C—> T) to be associated with asthma." (PMID 33133517, 2020). "A meta‐analysis of GWASs of self‐reported pollen, dust‐mite or cat allergy of 22 012 allergic subjects and 31 850 healthy controls showed that GSDMB gene (rs9303280, T‐> C) was most strongly associated with asthma." (PMID 33133517, 2020). "Further, we perform in vitro perturbation experiments on a widely replicated asthma gene, GSDMB, showing that FC identifies candidate mediators of the interactions between GSDMB and COPD-associated genes." (PMID 32041952, 2020). "GSDMB appears to be associated with asthma and certain types of autoimmune diseases such as, type 1 diabetes, inflammatory bowel disease, and rheumatoid arthritis." (PMID 30621583, 2019). "Several variants were associated earlier onset of asthma (7445 asthma-only cases)—the strongest being rs921650 in GSDMB (17q21 region)." (PMID 31921716, 2019). "They found evidence of association of pLoF variants located at well-known IL33 and GSDMB asthma loci with lower risk of both asthma and allergic rhinitis." (PMID 30805318, 2019). "Our results suggest that knocking out just one copy of GSDMB provides most of the protective effect on asthma risk." (PMID 29691392, 2018). "Variants that increase expression of GSDMB in humans are associated with asthma risk, and increased GSDMB expression causes an asthma phenotype in mice." (PMID 29691392, 2018). "More specifically, our group identified in MS patients, for the first time, one dysregulated circRNA derived from GSDMB, a gene associated with susceptibility to asthma and autoimmune diseases." (PMID 30619471, 2018).
asthma (continued). "We also identified protective associations for the PTV rs11078928 (MAF = 47.1%) in GSDMB against asthma (p = 6.3 × 10−50, OR = 0.90, 95% CI: 0.88–0.91) and bronchitis (p = 2.6 × 10−6, OR = 0.91, 95% CI: 0.87–0.95)." (PMID 29691392, 2018). "GSDMB is associated with asthma in humans and induces an asthma phenotype in mouse when overexpressed." (PMID 29691392, 2018). "GSDMB in the established 17q21 childhood asthma risk region is potentially involved in pathogenesis via epithelial cell pyroptosis." (PMID 30373671, 2018). "We identified pLOF variants in IL33 (encoding interleukin 33) and GSDMB (encoding gasdermin B) as associated with a lower risk of asthma." (PMID 29691411, 2018). "The focus of the present work was the characterization of GSDMB, an alternatively-spliced gene located on the 17q12 locus, which was repeatedly associated with susceptibility to asthma and to several AIDs." (PMID 28272342, 2017). "A recent study presumed that HRV-stimulated peripheral blood mononuclear cells increased the gene expression of ORMDL3 and of GSDMB which was associated with 17q21 variants and correlated with development of asthma." (PMID 28270165, 2017). "The SNP rs7216389, claimed to be a risk factor for asthma, is present in the intron of the neighboring gene Gasdermin B (GSDMB) and has been shown to modulate expression of both genes." (PMID 27835674, 2016). "Of these, five missense mutations (one each in FAM134B, NPC1L1, IKZF1, SLC26A3 and GSDMB) showed evidence of association with asthma in the combined sample, two of which (IKZF1 and SLC26A3) were more significant in the African ancestry sample." (PMID 25591454, 2015). "We demonstrated association of ADAM33, IL4 and ORMDL3/GSDMB gene polymorphisms with childhood asthma." (PMID 25768087, 2015). "Our study suggests rs2305479 as a good candidate for the causal variant at this important locus and implicates GSDMB more directly in asthma risk." (PMID 25591454, 2015). "Variants in GSDMB have been shown to determine multiple asthma related phenotypes specifically in childhood asthma including associations with lung function and disease severity." (PMID 25477900, 2014). "Although the functional significance of these changes remains to be determined, our study provides further evidence that GSDMB is a promising candidate gene at the 17q12-21 locus, in altering susceptibility to various autoimmune diseases, and asthma." (PMID 24044605, 2013). "Our results provide further support for the role of GSDMB SNPs in determining multiple asthma related phenotypes in childhood asthma including associations with lung function and disease severity." (PMID 24066901, 2013). "A GSDMB SNP at the 17q21 locus, rs2305480 (Ser311Pro) was associated with asthma diagnosis, with the T allele conferring risk to develop asthma as previously reported (p = 8.9×10-4, z = -3.23)." (PMID 24066901, 2013). "By providing insights that may guide future research and treatment approaches, this comprehensive analysis seeks to elucidate how GSDMB genetic variants impact asthma susceptibility." (PMID 39906448, 2025). "The rs7216389 TT variant on 17q21 may be an independent risk factor for exacerbations in adults with type 2–low asthma, highlighting the role of GSDMB in its pathophysiology." (PMID 40687950, 2025). "Further, a SNP in GSDMB (rs7216389) was also found to be associated with chronic rhinosinusitis, an inflammatory condition affecting the nasal and sinus mucosa, correlating strongly with the occurrence of asthma." (PMID 40133993, 2025). "Additionally, recent studies have shown a potential gene-gene interaction between ORMDL3 and GSDMB, with co-expression of both genes linked to increased asthma susceptibility." (PMID 39906448, 2025).
asthma (continued). "We found strong associations between childhood asthma and variants near gasdermin B (GSDMB) and zona pellucida‐binding protein 2 (ZPBP2) on chromosome 17q21.1 (e.g., rs4795399‐T, odds ratio = 1.43, p value = 1.61E−23), which is consistent with previous studies." (PMID 40133993, 2025). "The rs6967330 variant in cadherin-related family member 3 (CDHR3), which encodes a receptor for human rhinovirus C, was also analyzed, because studies on CDHR3 in adults are limited, despite its identification as a risk factor for asthma exacerbation in children similarly to GSDMB/ORMDL3." (PMID 40687950, 2025). "Thus, the objective of the present literature review is to assess the role of pathological and genetic factors in childhood asthma, with a focus on the rs7216389 polymorphism of the GSDMB gene." (PMID 40104184, 2024). "For example, GSDMB may be implicated in the pathogenesis of asthma, loss of DFNB59 function may lead to hearing loss, and widely expressed GSDMD is potentially implicated in the pathogenesis of various diseases across multiple organs and systems." (PMID 38584157, 2024). "Despite the genetic association between GSDMB and asthma, the precise biological role of GSDMB in asthma development remains unclear." (PMID 40104184, 2024). "A splice variant causing the deletion of exon 6, which encodes 13 amino acids in the N-terminal domain, has been reported to decrease the risk of asthma, suggesting that abolishing GSDMB-mediated pyroptotic activity may play a role in asthma." (PMID 38225586, 2024). "Increased GSDMB expression and the asthma-risk allele are correlated in all of these organs." (PMID 40104184, 2024). "Furthermore, the review aims to investigate the biological impact of the identified polymorphism rs7216389 regarding childhood asthma development and progression and GSDMB frequency in various types of cells as well as gene regulation mechanisms." (PMID 40104184, 2024). "In this detailed study, the review seeks to better understand how the genetic variations in GSDMB affect the predisposition to asthma, which may be important to the next studies and treatment plans." (PMID 40104184, 2024). "Moderate evidence exists for associations of the GSDMB rs7216389 variants with asthma." (PMID 36911417, 2023). "Furthermore, a splice variant of GSDMB (rs11078928) is related to a lower risk of asthma since the deletion of a key exon in the GSDMB transcript neutralizes its ability to induce pyroptosis." (PMID 37250902, 2023). "GSDMB is a functional gene for both asthma susceptibility and severity." (PMID 36911417, 2023). "This phenomenon may explain why different GSDMB genotypes are associated with various phenotypes of adult asthma." (PMID 35967302, 2022). "This suggests different pathogenic effects of GSDMB variants in asthma." (PMID 35281099, 2022). "A GWAS study has identified immune-related gene variants (e.g., FLG and GSDMB) shared by asthma, hay fever and AD, suggesting that these allergic diseases may share the same mechanism that leads to dysregulation of immune-related genes." (PMID 36245730, 2022). "Moreover, a study that was held on Japanese also confirmed such association between rs7216389 SNP of GSDMB with asthma in children." (PMID 36201519, 2022). "Taking together these data, we propose that the SNPs of GSDMA/GSDMB genes may increase susceptibility to asthma in childhood and adulthood populations through augmentation of IgE production." (PMID 36201519, 2022). "ORMDL3 and gasdermin B. GWAS suggest that chromosome 17q21 is linked to asthma." (PMID 36078171, 2022). "The reduced LD on African-ancestry chromosomes and the eQTL effects have recently been leveraged for fine mapping, revealing that the association with childhood-onset asthma at this locus is due to genetic variation influencing the expression of GSDMB, particularly in airway epithelial cells." (PMID 36175932, 2022).
asthma (continued). "Additionally, a splicing variant (rs11078928) of GSDMB can reduce asthma risk as this variant can abolish GSDMB‐mediated pyroptosis by deleting 13 amino acids in the N‐terminus of GSDMB." (PMID 34590363, 2021). "The fifth variant, rs4795400 in GSDMB, showed a stronger effect on the age-of-onset of asthma." (PMID 32603359, 2020). "There is some evidence that a GSDMB splice variant, associated with lower asthma risk, causes an exon deletion leading to GSDMB protein losing its ability to induce pyroptosis in airway epithelial cells, possibly reducing asthma risk." (PMID 33133517, 2020). "IBD and asthma also share a common genetic susceptibility, which includes a polymorphism of gasdermin-B (GSDMB), a protein responsible for regulating differentiation and growth of epithelial cells, as well as a polymorphism for the Interleukine 23 receptor gene." (PMID 32549223, 2020). "We therefore examined whether asthma-associated pLOF variants in GSDMB and IL33 associate with a lower risk of other atopic disorders in UK Biobank." (PMID 29691411, 2018). "GSDMB has been proposed to be the causative gene associated with asthma." (PMID 27658857, 2016). "In the Swedish birth-cohort BAMSE, Acevedo and colleagues studied the association of childhood asthma with SNPs, regional DNA methylation, and gene expression at the GSDMB/ORMDL3 locus located at 17q21, a well-studied asthma-susceptibility locus found in ethically diverse populations." (PMID 27777592, 2016). "Acevedo and colleagues studied the association of childhood asthma with CpG sites polymorphisms, regional DNA methylation and gene expression at the GSDMB/ORMDL3 locus, which is located at 17q21, a novel asthma-susceptibility locus found in ethically diverse populations." (PMID 26668064, 2015). "Furthermore, it was recently reported that polymorphisms with GSDMA and GSDMB loci are associated with asthma, atopy and intermediate phenotypes such as elevated immunoglobulin E." (PMID 23979942, 2013). "This study examined whether children with asthma have the polymorphism rs7216389 in the GSDMB gene." (PMID 39906448, 2025). "Additionally, GSDMB has been identified as a key genetic determinant potentially influenced by a dosage effect, meaning that the number of risk alleles can affect the severity of asthma." (PMID 39906448, 2025). "Notably, the expression of ORMDL3 (encoding ORMDL sphingolipid biosynthesis regulator 3) and GSDMB (encoding gasdermin B), both asthma-associated genes located in the 17q21 locus, was significantly elevated in RV-stimulated peripheral blood mononuclear cells (PBMCs) compared to unstimulated PBMCs." (PMID 40806756, 2025). "Additionally, hypomethylation at the ORMDL3 and GSDMB loci within the 17q21 asthma susceptibility region has been observed in children with early-onset asthma and rhinovirus-related wheezing, underscoring their potential in risk prediction and personalized treatment planning." (PMID 40806756, 2025). "Recent studies have revealed the diverse molecular functions of GSDMB and its close association with various diseases, particularly cancers (e.g., breast cancer, gastric cancer, bladder cancer) and inflammatory diseases (e.g., asthma, inflammatory bowel disease)." (PMID 40452932, 2025). "However, whether the genetic determinant, Gasdermin B (GSDMB), the most replicated asthma risk gene, regulates this pathway remains unknown." (PMID 38737375, 2024). "Therefore, we could not determine whether the novel alleles by themselves contribute to asthma risk or whether increased expression of GSDMA modifies risk only in the presence of increased GSDMB expression." (PMID 36175932, 2022). "They suggested that ORMLD3/GSDMB region could play a role in susceptibility and high-risk development of asthma, by increasing total IgE production which was enhanced by external environmental interplays such as tobacco smoke or viral infections, but not allergic sensitization or allergic rhinitis." (PMID 36201519, 2022).
asthma (continued). "Moreover, gene polymorphism of GSDMB is highly correlated with the pathogenesis of asthma." (PMID 35967302, 2022). "Moreover, the expression of ORMDL3 (encoding ORMDL sphingolipid biosynthesis regulator 3) and of GSDMB (encoding gasdermin B), the 17q21 genes related to asthma, was significantly higher in RV-stimulated compared to the unstimulated peripheral blood mononuclear cells (PBMCs)." (PMID 33668787, 2021). "Indeed, sQTLs for GSDMB are among the top associated variants with asthma in42." (PMID 33526779, 2021). "In this study, we identified pLOF variants that protect against obesity (GPR151), asthma (GSDMB, IL33), autoimmune disorders (IFIH1), and coronary artery disease (PDE3B), prioritizing genes and pathways for which pharmacologic attempts to mimic these protective mutations might ameliorate disease." (PMID 29691411, 2018). "The functional gene GSDMB, located on chromosome 17q12-21, has been shown in prior research to directly contribute to the immunological response in asthma, including inflammation and epithelial cell function control." (PMID 39906448, 2025). "Another interesting example is the IKZF3/GSDMB/ORMDL3 GWAS locus, which is linked to many autoimmune diseases, including RA, asthma, systemic sclerosis (SSc), and others." (PMID 39930543, 2025). "The goal is to identify the function of the GSDMB gene in inflammatory and immunological processes and investigate how it affects asthma differently in adults and children." (PMID 39906448, 2025). "This article provides a comprehensive overview of asthma pathogenesis, emphasizing the significance of genetic markers like rs7216389 in the GSDMB gene." (PMID 39906448, 2025). "The rs7216389 polymorphism influences asthma in children by altering the expression of genes like ORMDL3 and gasdermin B (GSDMB), which are involved in immune regulation and airway inflammation." (PMID 39906448, 2025). "Studies have shown that higher expression levels of GSDMB correlate with increased asthma severity and a greater number of exacerbations." (PMID 39906448, 2025). "The involvement of GSDMB/ORMDL3 in type 2–low asthma is further illustrated by the effect of ORMDL3 on sphingolipid dysregulation." (PMID 40687950, 2025). "As we did not see an association with the causal asthma SNP rs2304580 or at least one of the SNPs in GSDMB or ORMDL3, it suggests that the genetic risk at this locus for both asthma and for RSV infection (severity and viral load) are different." (PMID 40867500, 2025). "We sought to clarify the association between variants in gasdermin B/orosomucoid-like 3 (GSDMB/ORMDL3) on 17q21 and exacerbations in type 2–low asthma." (PMID 40687950, 2025). "Gasdermin B (GSDMB), encoded in the asthma susceptibility locus 17q21, harbors SNPs that increase disease risk." (PMID 41394843, 2025). "In asthma, over 212 genomic loci have been identified to date, including loci harboring GSDMB/ORMDL, HLA, TSLP, IL1RL1/Il18R, and IL3310,15–18, confirming the important role of type 2 inflammatory pathways." (PMID 41213931, 2025). "Beyond its diverse functions in cancer, GSDMB has garnered significant attention for its involvement in inflammatory diseases, including asthma, inflammatory bowel disease, and viral infections." (PMID 40452932, 2025). "The article also aims to investigate gene regulatory mechanisms, the biological impact of rs7216389 on the development of pediatric asthma, and the prevalence of GSDMB in different cell types." (PMID 39906448, 2025). "One important piece of evidence regarding circRNAs is the changes in the expression levels of Gasdermin B (GSDMB), a gene frequently related to asthma susceptibility and autoimmune disorders." (PMID 38396932, 2024). "There is a significant correlation between polymorphisms in GSDMB and the propensity to develop chronic inflammatory disorders such as IBD, type I diabetes, and asthma." (PMID 38584157, 2024).